TRPM4 (transient receptor potential cation channel subfamily M member 4)
Diseases named in the same sentence as TRPM4 in open-access papers (continued):
Sharing a sentence is not in itself a finding about the gene and the disease.
cerebral edema (11 papers, 2016 to 2024). "To further explore the correlation between impaired glymphatic system function and cerebral edema, we used Trpm4-knockout (Trpm4–/–) mice and glibenclamide treatment to alleviate cerebral edema after SE." (PMID 34494549, 2021). "To explore the influence of cerebral edema on glymphatic system function, we used genetic deletion of Trpm4 and glibenclamide treatment to reduce cerebral edema." (PMID 34494549, 2021). "Targeted investigations into the impact of ABCC8 and TRPM4 genetic variation on cerebral edema, intracranial hypertension, and outcome after TBI have been performed in 385–485 patients with severe TBI from a single-center." (PMID 31936452, 2020). "Additionally, studies have shown an association between intracranial pressure or cerebral edema after brain injury and several genetic SNP loci in these genes (ABCC8 and TRPM4)." (PMID 35474489, 2022). "Apart from TRPM4, other possible drug targets of cerebral edema were also detailed." (PMID 35056097, 2021). "In spite of recent treatment targets for cerebral edema and ICP including the Na+-K+-2Cl− co-transporter (NKCC1) and the SUR1-regulated NCCa-ATP (SUR1/TRPM4) channel, osmotherapy remains typically administered." (PMID 27487831, 2016). "The role of the sulfonylurea receptor 1 (SUR1)–transient receptor potential melastatin 4 (TRPM4) non-selective cation channel in cerebral edema was demonstrated by extensive studies." (PMID 35474489, 2022).
endometrial cancer (10 papers, 2020 to 2025). Primary or metastatic malignant neoplasm involving the endometrium (mucous membrane that lines the endometrial cavity). "In contrast, increased expression of TRPM4 in endometrial carcinoma cells is associated with a more favorable prognosis." (PMID 36158191, 2022). "In combination with six other genes (PHLDA2, GGH, ESPL1, FAM184A, LMNB1, and KIAA1644), TRPM4 performed well as a diagnostic prediction signature for endometrial cancer." (PMID 33562811, 2021). "The role of TRPM4 in the cancer hallmark functions of endometrial cancer was recently studied." (PMID 33562811, 2021). "Our study considered TRPM4 a protective prognostic gene in endometrial cancer, which was consistent with our previous report." (PMID 36231119, 2022). "In vitro experiments showed a decline in TRPM4 expression in response to estrogen stimuli in endometrial cancer, possibly involved in cancer cell proliferation and migration." (PMID 36230654, 2022). "TRPM4 expression was also analyzed in endometrial cancer with a public data-based expression analysis." (PMID 33562811, 2021). "Overall, these results suggest that, like in tissue biopsies, the expression of TRPV2 and TRPC1 are associated with increased EMT status (or invasiveness), while TRPM4 expression is correlated with a low EMT status in endometrial cancer cells." (PMID 34936030, 2021). "Endometrial carcinoma with reduced TRPM4 mRNA expression significantly correlated with poor prognosis, as well as overall and recurrence-free survival, making TRPM4 a prognostic factor." (PMID 35056097, 2021). "The TRPM4 silencing in endometrial cancer AN3CA cells promoted proliferation and migration." (PMID 36230654, 2022). "Consequently, TRPM4 knockdown increases the migratory ability of endometrial carcinoma (AN3 CA) cells." (PMID 36158191, 2022). "Moreover, a recent expression study of 491 endometrial cancer patients revealed that decreased TRPM4 mRNA expression is significantly correlated with a poor prognosis and reduced overall survival." (PMID 33562811, 2021). "Thus far, TRPM4 has been investigated in diffuse large B-cell lymphoma, prostate, colorectal, liver, breast, urinary bladder, cervical, and endometrial cancer." (PMID 33562811, 2021). "Moreover, TRPM4 silencing in endometrial cancer cells increased expression of EMT markers, possibly via increased signaling of the PI3K/AKT/mTOR pathway." (PMID 34360952, 2021). "Contrary to the results described for many other cancer types, silencing of TRPM4 increased the cell viability and migration rate of AN3CA endometrial cancer cell line." (PMID 33562811, 2021). "Accordingly, TRPM4 silencing increased the cell viability and migration rate of the AN3CA endometrial cancer cell line." (PMID 35056097, 2021).
heart failure (10 papers, 2016 to 2025). Inability of the heart to pump blood at an adequate rate to meet tissue metabolic requirements. "In addition, an enhanced β-adrenergic cardiac reserve was observed in TRPM4-deficient mice under conditions of ischemia evoked heart failure compared to wildtype controls." (PMID 33205255, 2020). "The expression of TRPM4 protein and the magnitude of TRPM4 current have been shown to be upregulated in either freshly isolated or cultured human ventricular fibroblasts of heart failure patients." (PMID 36277180, 2022). "Nevertheless, TRPM4 protein expression was also higher (about twice as much) in human left ventricular tissue samples of heart failure patients compared with samples from healthy donor hearts." (PMID 35056097, 2021). "Consequently, cardiomyocyte-specific inactivation of the TRPM4 function appears to be a promising strategy to improve cardiac contractility in heart failure patients." (PMID 33580817, 2021). "This strategy represents a promising approach to test whether TRPM4 knockdown leads to an increase in inotropic response in healthy animals and particularly in heart failure models." (PMID 33580817, 2021). "Recently a strategy using in vivo AAV9-RNAi-mediated silencing of cardiac TRPM4 was developed in the hope of increasing the cardiac contractility in animal models of cardiac failure, where a 90% reduction of TRPM4 protein expression was achieved in the adult mouse heart." (PMID 35056097, 2021). "Thus, the concept of inhibiting TRPM4 channels or suppressing their expression needs to be explored in different genetically diverse populations of patients suffering from cardiac failure." (PMID 33205255, 2020). "Previously, however, the increase of TRPM4 expression was reported in various pathological conditions such as in rats with spontaneous hypertension, in infarcted mouse left ventricle, and in NYHA stage 3–4 human heart failure patients." (PMID 34502410, 2021).
multiple sclerosis (9 papers, 2014 to 2024). A progressive autoimmune disorder affecting the central nervous system resulting in demyelination. "Gli is a hypoglycemic agent that can inhibit NLRP3 mediated production of IL-1β by blocking P2X7 ion-channels; this compound also modulates TRPM4, a cation channel that mediates axonal and neuronal degeneration in Multiple Sclerosis (MS)." (PMID 38139851, 2023). "Despite that, additional experiments are required to better understand that molecular pathways of TRPM4 in neurological disorders, such as multiple sclerosis." (PMID 29996905, 2018). "In conclusion, accumulating evidence indicates a crucial role of TRPM4 in EAE as well as in multiple sclerosis, confirming TRPM4 as a strong potential therapeutic target in these diseases." (PMID 29996905, 2018). "In EAE and multiple sclerosis, TRPM4 channels were reported to be predominantly expressed by reactive astrocytes in pathologically involved tissues that exhibit a significant inflammatory burden, such as spinal cords." (PMID 29996905, 2018). "The transient receptor potential melastatin 4 (TRPM4) channel contributes to disease severity in the murine experimental autoimmune encephalomyelitis (EAE) model of multiple sclerosis and to neuronal cell death in models of excitotoxicity and traumatic brain injury." (PMID 35397639, 2022). "Finally, our findings here with TRPM4 may also be relevant for understanding the neuroprotective actions of icilin in mouse models of multiple sclerosis and seizures." (PMID 39485376, 2024). "Furthermore, TRPM4 is involved in the neurogenerative process of multiple sclerosis." (PMID 34771564, 2021). "As we previously demonstrated that TRPM4-lacking mice have improved outcomes in the EAE model of multiple sclerosis and that Trpm4–/– neurons are protected from excitotoxicity, we also examined the role of TRPM4 in synaptic transmission at the acute phase of EAE1." (PMID 35397639, 2022).
cervical cancer (8 papers, 2016 to 2024). A primary or metastatic malignant neoplasm involving the cervix. "A gene expression study of cervical cancer cases reported that TRPM4 was overexpressed in cervical cancer specimens compared with normal cervical epithelium." (PMID 36230965, 2022). "A gene expression study of cervical cancer cases reported TRPM4 to be overexpressed in cervical cancer specimens compared to normal cervical epithelium." (PMID 33562811, 2021). "shRNA-mediated TRPM4 downregulation was shown to lead to decreased cell proliferation in the cervical-cancer-derived cell line HeLa." (PMID 33562811, 2021). "TRPM4 transcript was also overexpressed in cervical cancer cases compared with normal cervical epithelium samples." (PMID 32484822, 2020). "For this reason, TRPM4 is identified as a key actor in cervix cancer development via the modulation of the β-catenin pathway, whose impairment is frequently associated with this cancer." (PMID 29875336, 2018). "TRPM4 has also been suggested to regulate cell proliferation, where suppression of TRPM4 decreased cervical cancer cell proliferation via β-catenin degradation." (PMID 27443843, 2016). "Furthermore, based on the fact that TRPM4 is a channel located on the cell membrane, it will be an interesting target on inhibiting proliferation of cervical cancer cells." (PMID 36230965, 2022). "TRPM4 is negatively correlated with the proliferation of cervical cancer HeLa cells." (PMID 36072430, 2022). "On the contrary, in the cervical-cancer-derived cell line HeLa shRNA-mediated TRPM4 downregulation led to decreased cell proliferation, while overexpression of TRPM4 in a HEK293-derived cell line (T-REx 293) increased cell proliferation via the β-catenin pathway." (PMID 35056097, 2021). "A reduced TRPM4 expression decreases proliferation of HeLa cervical cancer-derived cells." (PMID 29875336, 2018). "TRPM4 silencing was reported to promote GSK-3β-dependent degradation of β-catenin and reduce β-catenin/Tcf/Lef-dependent transcription to inhibit cervical cancer." (PMID 36072430, 2022).
experimental autoimmune encephalomyelitis (8 papers, 2015 to 2022). An autoimmune demyelinating disease of the central nervous system that is produced experimentally in animals by the injection of homogenized brain or spinal cord in Freund's adjuvant. "TRPM4 mediates neuronal degeneration and has been related to various neurological disorders like experimental autoimmune encephalomyelitis and MS19." (PMID 32943671, 2020). "In experimental autoimmune encephalomyelitis, TRPM4 inhibition protects neurons against neuroinflammation." (PMID 31664513, 2019). "Among them, recent findings underlined the transient receptor potential melastatin 4 cation channel (TRPM4) as a key player in neuronal degeneration in MS and experimental autoimmune encephalomyelitis (EAE)." (PMID 29996905, 2018). "Similarly, in a murine model of experimental autoimmune encephalomyelitis, silencing of Abcc8 or of Trpm4 results in the same phenotype, with reduced neuroinflammation and preservation of white matter." (PMID 27246103, 2016). "In murine experimental autoimmune encephalomyelitis (EAE), TRPM4 deletion and administration of glibenclamide were found to ameliorate clinical symptoms and attenuate disease progression." (PMID 29996905, 2018). "In experimental autoimmune encephalomyelitis (EAE), deletion of transient receptor potential melastatin 4 (Trpm4) and administration of glibenclamide were found to ameliorate disease progression, prompting speculation that glibenclamide acts by directly inhibiting Trpm4." (PMID 26581714, 2015).
Hypertension (8 papers, 2015 to 2024). The presence of chronic increased pressure in the systemic arterial system. "Since cholesterol accumulation causes kidney dysfunction and contributes to hypertension, the stimulation of TRPM4 by elevated cholesterol would have pathophysiological significance." (PMID 34054517, 2021). "Also, it was shown that TRPM4-deficient mice display moderate hypertension, which is a result of the increased level of catecholamines in blood plasma of TRPM4-deficient mice compared to WT." (PMID 26043922, 2015). "TAGLN with ACTA2 was hypothetically associated with TRPM4/6/7/8 Signalling in Arterial Hypertension (Hypothesis) (q = 1.016x10-2), Smooth Muscle Cell Dysfunction in Arterial Hypertension (q = 1.334x10-2), and TGF-Beta Family in Epithelial Mesenchymal Transition in Cancer (q = 1.878x10-2)." (PMID 39480826, 2024). "In a mouse model with genetic manipulation, TRPM4 deletion resulted in increased catecholamine secretion by AGCCs and hypertension." (PMID 33329690, 2020). "The modulation of TRPM4 activity may be a therapeutic target for hypertension." (PMID 35163382, 2022). "The studies conducted on these channels indicated that TRPM4, TRPC1, TRPC3, and TRPC6 channels play an important role in the creation and progression of hypertrophy and hypertension." (PMID 32641948, 2019).
long QT syndrome (8 papers, 2017 to 2024). "The long QT patient-specific iPSC line carrying KCNQ1/TRPM4 dual mutations also represents a tool for further understanding long QT syndrome pathogenesis." (PMID 36010573, 2022). "Drug screening based on cardiomyocytes derived from FAHXMUi001-A successfully identified verapamil and lidocaine as alternative therapeutic agents for the treatment of a rare KCNQ1/TRPM4 dual mutation long QT syndrome patient." (PMID 36010573, 2022). "Mutations of G219E and T160M in KCNQ1 and TRPM4, respectively, were found in a 37-year-old female long QT syndrome Uygur patient." (PMID 35056097, 2021). "The TRPM4 mutants, V441M and R499P, were almost absent in control populations, but the mechanism that describes how TRPM4 loss-of-function could lead to long QT syndrome is unknown." (PMID 35056097, 2021). "TRPM4 mutations were found in the atrioventricular block and the right-bundle branch block but not in sinus node dysfunction, Brugada, or long QT syndrome." (PMID 35056097, 2021). "Four TRPM4 mutations, but no other mutations of the 13 major long QT syndrome genes were found in approximately 2% of the 178 patient-containing cohort." (PMID 35056097, 2021). "Moreover, the T160M polymorphism of TRPM4 (together with the G219E of KCNQ1) was found in a family where carriers experienced long QT syndrome, which might implicate the role of TRPM4 in the maintenance of normal AP duration." (PMID 34502410, 2021). "Furthermore, no mutations were found in the DNA of these TRPM4 variant carriers in any of the 13 major long QT syndrome genes." (PMID 28315637, 2017).
channelopathies (7 papers, 2016 to 2021). "As a calcium-activated ion channel encoding gene, TRPM4 had already been extensively studied in a series of channelopathy-related reports, and some uncommon missense SNVs had been identified to be likely pathogenic in 20 out of 248 BrS patients and in 13 out of 330 SUD cases, respectively." (PMID 33895855, 2021). "The main objective of this article is to review the major cardiac TRPM4 channelopathies and recent advances regarding their genetic background and the underlying molecular mechanisms." (PMID 33381229, 2020). "Three cases (34, 286 and 290) had one variant in a cardiomyopathy gene and one in a channelopathy gene (CSRP3 and TRPM4, PKP2 and ANK2, MYH7 and KCNH2, respectively)." (PMID 30615648, 2019). "In Bern, the TRPM4 gene is screened routinely in cases with suspected channelopathies." (PMID 29568272, 2018). "Such TRP channelopathies include night blindness (TRPM1), progressive familial heart block type I (TRPM4), hypomagnesemia with secondary hypocalcemia (TRPM6), and autosomal dominant polycystic kidney disease (TRPP2), to name a few." (PMID 26490951, 2016).
diffuse large B-cell lymphoma (6 papers, 2021 to 2023). "TRPM4 mRNA upregulation (together with the downregulation of other genes) in CD5+ subtypes of diffuse large B-cell lymphoma (DLBCL) patients was associated with a poorer prognosis compared with CD5− patients." (PMID 35056097, 2021). "In addition, within normal lymphoid tissues, including the tonsils, lymph nodes, and appendix, human normal B cells express low levels of TRPM4, while in diffuse large B cell lymphoma, a higher TRPM4 protein level has been detected, which confers significantly poorer patient outcomes." (PMID 37892239, 2023). "In patients with CD5+ subtypes of diffuse large B-cell lymphoma (DLBCL), the upregulation of TRPM4 mRNA was related to a poorer prognosis compared to CD5− patients." (PMID 36844925, 2022). "It has been found that TRPM4 is significantly overexpressed in diffuse large B-cell lymphoma (DLBCL), compared to normal germinal centre (GC) B cells and, in addition, it is more expressed in activated B-cell-like than in GC DLBCL." (PMID 34065398, 2021). "In addition, in diffuse large B cell lymphoma (DLBCL), TRPM4 expression was increased in comparison to normal B cells and was associated with a poor prognosis for the patients." (PMID 34771564, 2021).
myocardial infarction (6 papers, 2018 to 2024). Gross necrosis of the myocardium, as a result of interruption of the blood supply to the area, as in coronary thrombosis. "Recently, it has been suggested that the TRPM4 channel is also involved in the development of cardiac ischemia-reperfusion injury, which causes myocardial infarction." (PMID 29914130, 2018). "Evidence from animal models illustrates that TRPM4 expression escalates under conditions such as myocardial ischemia-reperfusion, myocardial infarction, and hypoxia-reoxygenation." (PMID 39726787, 2024). "These diseases often arise or worsen due to myocardial infarction and hypoxia-reoxygenation injury, among other stress conditions, making the exploration of the interaction between Brg1 and TRPM4 of paramount importance." (PMID 39726787, 2024). "In contrast, TRPM4 was beneficial; moreover, it was essential for survival in a mouse model of myocardial infarction." (PMID 35056097, 2021). "Unlike unaltered TRPM4 mRNA expression in rats, murine TRPM4 expression increased at both the mRNA and protein levels in a mouse model of myocardial infarction." (PMID 35056097, 2021). "Global knockout of TRPM4 in mouse led to increased cardiac contractility under β-adrenergic stimulation, both under basal conditions and after induced myocardial infarction." (PMID 33580817, 2021). "Since TRPM4 has been designated as a functional agent of various diseases, including cancer and heart attack, it is necessary to describe in detail its function and modulation mechanisms." (PMID 32560560, 2020).
atrioventricular block (5 papers, 2020 to 2025). A heart block that is initiated in the atrioventricular node. "Later, the genetic screening of 91 patients with childhood atrioventricular block allowed the identification of five rare TRPM4 variants (p.D198G, p.A432T/G582S, p.T677I, and p.V921I)." (PMID 33381229, 2020). "Other TRPM4 variants (p.Q131H, p.Q293R, p.G582S, p.Y790H, p.K914X, and p.P970S) were identified in patients with right-bundle branch block and atrioventricular block." (PMID 33381229, 2020). "The link behind TRPM4 overexpression and the atrioventricular block was established by computational modeling, where the doubling of the TRPM4 currents led to EAD formation." (PMID 35056097, 2021).